H4C11 (H4 clustered histone 11)
Description:
Core component of nucleosome. Nucleosomes wrap and compact DNA into chromatin, limiting DNA accessibility to the cellular machineries which require DNA as a template. Histones thereby play a central role in transcription regulation, DNA repair, DNA replication and chromosomal stability. DNA accessibility is regulated via a complex set of post-translational modifications of histones, also called histone code, and nucleosome remodeling.
Synonyms: H4/E; H4FE; HIST1H4J; H4F2iv; TEBIVANED2; TEVANED2; dJ160A22.2
Target class: Other nuclear protein
Gene: Protein-coding gene on chromosome 6 (27,824,092 to 27,824,480, forward strand). Ensembl gene ENSG00000197238.
Subcellular location: Nucleus; Chromosome
Pathways (Reactome):
Gene expression (Transcription): B-WICH complex positively regulates rRNA expression; DNA methylation; ERCC6 (CSB) and EHMT2 (G9a) positively regulate rRNA expression; MLL4 and MLL3 complexes regulate expression of PPARG target genes in adipogenesis and hepatic steatosis; NoRC negatively regulates rRNA expression; PRC2 methylates histones and DNA; RNA Polymerase I Promoter Escape; RNA Polymerase I Promoter Opening; RUNX1 regulates genes involved in megakaryocyte differentiation and platelet function; RUNX1 regulates transcription of genes involved in differentiation of HSCs; Regulation of endogenous retroelements by KRAB-ZFP proteins; Regulation of endogenous retroelements by Piwi-interacting RNAs (piRNAs); Regulation of endogenous retroelements by the Human Silencing Hub (HUSH) complex; SIRT1 negatively regulates rRNA expression; Transcriptional regulation by small RNAs
Chromatin organization: CHD1 and CHD2 subfamily; CHD6, CHD7, CHD8, CHD9 subfamily; ChAHP complex assembly; HATs acetylate histones; HDACs deacetylate histones; HDMs demethylate histones; Interaction of NuRD complexes with transcription factors; NuRD complex assembly; PKMTs methylate histone lysines; RMTs methylate histone arginines
DNA Repair: Cleavage of the damaged purine; Cleavage of the damaged pyrimidine; Nonhomologous End-Joining (NHEJ); Processing of DNA double-strand break ends; Recognition and association of DNA glycosylase with site containing an affected purine; Recognition and association of DNA glycosylase with site containing an affected pyrimidine; Recruitment and ATM-mediated phosphorylation of repair and signaling proteins at DNA double strand breaks
Cell Cycle: Condensation of Prophase Chromosomes; Deposition of new CENPA-containing nucleosomes at the centromere; G2/M DNA damage checkpoint; Inhibition of DNA recombination at telomere; Packaging Of Telomere Ends
Developmental Biology: Activation of anterior HOX genes in hindbrain development during early embryogenesis; Chromatin modifications during the maternal to zygotic transition (MZT); Replacement of protamines by nucleosomes in the male pronucleus
and 20 more pathways
Gene Ontology:
Molecular function: protein binding; RNA binding; structural constituent of chromatin; DNA binding; protein heterodimerization activity
Biological process: negative regulation of megakaryocyte differentiation; nucleosome assembly; chromatin organization; protein localization to CENP-A containing chromatin; telomere organization
Cellular component: CENP-A containing nucleosome; chromosome, telomeric region; extracellular exosome; membrane; nucleoplasm; nucleosome; nucleus; protein-containing complex; extracellular region; chromosome
Genetic constraint (gnomAD): Loss-of-function variants: 1 observed, 3.69 expected, observed/expected ratio (o/e) 0.27, 90% interval 0.095 to 1.26. That is too few expected variants to judge how well the gene tolerates losing a copy. Missense variants: 73 observed, 137 expected, observed/expected ratio (o/e) 0.53, 90% interval 0.44 to 0.65. Synonymous variants: 95 observed, 54.46 expected, observed/expected ratio (o/e) 1.74, 90% interval 1.47 to 1.96.
Homologues: Orthologues: chimpanzee H4C6 (100% identical), dog H4C4 (100% identical), macaque H4C4 (100% identical), mouse H4c6 (100% identical), rat Hist1h4b (100% identical), tropical clawed frog h4c3 (100% identical). Paralogues in human: H4C1 (100% identical), H4C12 (100% identical), H4C13 (100% identical), H4C14 (100% identical), H4C15 (100% identical), H4C16 (100% identical), H4C2 (100% identical), H4C3 (100% identical), H4C4 (100% identical), H4C5 (100% identical), H4C6 (100% identical), H4C8 (100% identical), and 2 more.
Diseases named in the same sentence as H4C11 in open-access papers:
H4C11 is named in the same sentence as 5 diseases in open-access papers, as found by Europe PMC text mining. Sharing a sentence is not in itself a finding about the gene and the disease. The quoted sentences say what the papers report.
non-Hodgkin lymphoma (1 paper, 2024). Distinct from Hodgkin lymphoma both morphologically and biologically, non-Hodgkin lymphoma (NHL) is characterized by the absence of Reed-Sternberg cells, can occur at any age, and usually presents as a localized or generalized lymphadenopathy associated with fever and weight loss. "Our study, supporting the use of five approaches, including TMT, gene ontology (GO), Reactome, KEGG pathway, and molecular docking analyses, suggests that DEPs, Myh3, Eno2, and H4c11 may be three novel biomarkers or therapeutic targets for non-Hodgkin lymphoma." (PMID 39861068, 2024).
osteosarcoma (1 paper, 2022). A usually aggressive malignant bone-forming mesenchymal neoplasm, predominantly affecting adolescents and young adults. "Interestingly, H4C11 mRNA was previously found to be polyadenylated in human osteosarcoma cells, following knockdown of SLBP, but not polyadenylated in other studies." (PMID 36447390, 2022).
cancer (1 paper, 2022). A tumor composed of atypical neoplastic, often pleomorphic cells that invade other tissues. "Meanwhile, only a few studies on H2BC14 and H4C11 in cancer have been reported." (PMID 36407085, 2022).
H4C11 also shares sentences with these, for which no sentence is quoted: systemic lupus erythematosus (2 papers); alcoholism (1).